SCCPDH (saccharopine dehydrogenase (putative))
Synonyms: CGI-49; NET11; CGI49
Tractability: Antibody: its Gene Ontology location is reachable by antibodies, with high confidence. PROTAC: ubiquitination databases record sites on it; its protein half-life has been measured.
Gene: Protein-coding gene on chromosome 1 (246,724,064 to 246,768,137, forward strand). Ensembl gene ENSG00000143653.
Subcellular location (Human Protein Atlas): Vesicles
Pathways (Reactome):
Hemostasis: Platelet degranulation
Gene Ontology:
Biological process: glycolipid biosynthetic process
Cellular component: lipid droplet; membrane; midbody; mitochondrion; nucleus; extracellular region; platelet alpha granule lumen
Genetic constraint (gnomAD): Loss-of-function variants: 12 observed, 15.11 expected, observed/expected ratio (o/e) 0.79, 90% interval 0.51 to 1.29. The upper end of that interval is the gene's LOEUF score, 1.29, which puts it in group 5 of 6, group 1 being the genes least tolerant of losing a copy. Missense variants: 194 observed, 187.03 expected, observed/expected ratio (o/e) 1.04, 90% interval 0.92 to 1.17. Synonymous variants: 83 observed, 72.41 expected, observed/expected ratio (o/e) 1.15, 90% interval 0.96 to 1.38.
Homologues: Orthologues: chimpanzee SCCPDH (99% identical), macaque SCCPDH (99% identical), dog SCCPDH (87% identical), mouse Sccpdh (87% identical), pig SCCPDH (86% identical), rat Sccpdh (86% identical), guinea pig SCCPDH (84% identical), tropical clawed frog sccpdh (68% identical), zebrafish sccpdha.1 (61% identical), zebrafish sccpdhb (60% identical), zebrafish sccpdha.2 (59% identical), Drosophila melanogaster CG2604 (39% identical), and 4 more.
Diseases named in the same sentence as SCCPDH in open-access papers:
SCCPDH is named in the same sentence as 3 diseases in open-access papers, as found by Europe PMC text mining. Sharing a sentence is not in itself a finding about the gene and the disease.
SCCPDH shares sentences with these, for which no sentence is quoted: Anxiety (1 paper); cystic fibrosis (1); depression (1).